PTCH1 (patched 1)
Diseases named in the same sentence as PTCH1 in open-access papers (continued):
Sharing a sentence is not in itself a finding about the gene and the disease.
tumor (continued). "Since the tumor lesions present at 2 months of age in Ptch1+/-/Tis21-/- mice develop invariably into a MB, these data represent a proof of concept that the treatment with Cxcl3 can reduce MB formation." (PMID 28018222, 2016). "The tumor suppressor role of PTCH1 has been further studied in transgenic mouse models that are heterozygous for a PTCH1 null mutation." (PMID 26891329, 2016). "The human tumor data paralleled our cell line findings in that there was high PTCH1, SMO, GLI2, and GLI3 mRNA, but low GLI1 mRNA." (PMID 27793025, 2016). "The only MYCN amplification was found in a case with a 9q deletion encompassing the PTCH1 locus, which strongly suggests this tumor belongs to the SHH subgroup." (PMID 26857864, 2016). "There was also elevated mRNA expression of Shh-signaling pathway genes Gli1, Gli2, Gli3 and Ptch1/2 in both tumor-adjacent skin and BCCs of IR-irradiated mice." (PMID 26413810, 2015). "Spontaneous tumor growth in the Ptch1+/−/SKH-1 animals was age-dependent, and usually occurred beyond 18 weeks of age when visible macroscopic BCCs begin to appear." (PMID 26413810, 2015). "Pairwise unsupervised clustering using a subset of the most variant genes (top 5%, n=1,076) showed that both types of CRISPR-Ptch1 tumours are most similar to germline Ptch1+/− and Atoh1-CreER;Ptch1fl/fl16 MB models." (PMID 26067104, 2015). "We analysed the tumours induced by somatic Ptch1 deletion using amplicon-based sequencing and whole-genome sequencing (WGS)." (PMID 26067104, 2015). "Several of these agents have induced tumour response in patients with tumours that harbour mutations in SMO and PTCH1, such as BCC and MB." (PMID 25660620, 2015). "To further characterize the tumor microenvironment, we investigated the status of effector pro-inflammatory signaling pathways in the tumor-adjacent skin and BCCs in Ptch1+/−/SKH-1 mice." (PMID 26413810, 2015). "Reduced expression of cyclin D1/N-cadherin in residual tumors coupled with static tumor growth confirmed the importance of p50/Bcl3 in the growth of BCCs in our Ptch1+/−/SKH-1 mice." (PMID 26413810, 2015). "In this regard, the Ptch1+/−/SKH-1 mouse more closely mimics patients with NBCCS who often develop BCCs in the first decade of life after which the rate of tumor growth typically increases with age." (PMID 26413810, 2015). "As a tumor suppressor gene, PTCH1 inhibits tumor cell growth and motility by blocking the Hh signaling pathway." (PMID 24961235, 2014). "We also compared a recent reported MM tumor stem marker PTCH1 and found that the expression of bFGF and PTCH1 are concurrently increased." (PMID 25053990, 2014). "The membrane-associated patched receptor 1 (Ptch1) and smoothened co-receptor (Smo) were detected exclusively in CD133+ cells containing tumor samples R18 and R28 using RT-PCR and SDS-PAGE Western blot analysis." (PMID 24978848, 2014). "In tumors with activated Hh signaling, high levels of PTCH-1 have been reported, especially within the tumor stroma." (PMID 25276795, 2014). "Mutations in PTCH1, the homologue of drosophila segment polarity gene patched, have been found in GS patients, and this spectrum of neoplasms is thought to arise due to a malfunction of PTCH1." (PMID 23951062, 2013). "Here, we report on the generation of Ptch1+/− Nos2−/− mice to investigate the impact of Nos2 on tumor development in Ptch1 hemizygous mutant mice." (PMID 22438824, 2012). "To identify those Nos2-dependent effects promoting MB induction, we determined the features that were common to Ptch1+/+ Nos2−/− and Ptch1+/− Nos2−/− genotypes and persisted in the tumor tissues." (PMID 22438824, 2012).
tumor (continued). "Differential expression of selected candidate genes was validated by qRT-PCR on an expanded, partially overlapping tumor set of seven Ptch1+/− Nos2+/+ versus seven Ptch1+/− Nos2−/− MB samples." (PMID 22438824, 2012). "For example, we were able to narrow down a region on 9q that, among others, included the PTCH1 gene that previously has been postulated as a UC specific tumor suppressor gene." (PMID 22685613, 2012). "As expected, the expression level of both PTCH1 and PTCH2, which code for the receptors Ptch1 and Ptch2, was lower in tumour samples than in normal tissue, possibly participating in the Hh pathway activation." (PMID 22361633, 2012). "Multiple somatic mutations of PTCH1 are recorded in COSMIC, consistent with its tumour suppressor role." (PMID 21781349, 2011). "In the majority the deletion contains the PTCH1 gene, which signifies that the patients in addition to the common mental retardation also develop the tumor proneness syndrome of Gorlin, which is to be taken into account in counseling and follow-up." (PMID 21693067, 2011). "PTCH1 is a tumour suppressor and acts as a receptor for the hedgehog ligands and inhibits the function of smoothened." (PMID 21781349, 2011). "In MB tumors that form in Ptch1+/− mice, Shh signaling is constitutively active and blocking this signal with a Shh-antagonist promotes tumor regression, highlighting the importance of Shh signaling in the initiation and maintenance of this tumor type." (PMID 21437245, 2011). "We also assessed the methylation status of the Cyclin D2 and PTCH1 promoters in these 14 cell lines and 58 primary tumor samples." (PMID 21059263, 2010). "In order to determine which cells were affected by cyclopamine treatment, we measured expression of Ptch1 and Gli1 mRNA, transcriptional targets of Hh signaling, in both the xenografted human tumor cells as well as the mouse stromal compartment." (PMID 20098680, 2010). "The PTCH1 promoter was hypermethylated in mice tumor models as demonstrated by changes in PTCH1 expression after treatment with demethylating agents." (PMID 21059263, 2010). "One group used immunohistochemistry to detect expression Hh targets PTCH1 and Gli1 in the tumor specimens whereas we and others assessed the expression of Hh target genes by several methods: in-situ hybridization, real-time PCR and immunohistochemistry." (PMID 19943941, 2009). "Mutations in PTCH1 gene have been reported in nevoid basal cell carcinoma syndrome (NBCCS), familial BC and its loss induced tumor progression in basal cell carcinoma (BCC)." (PMID 18990233, 2008). "Lack of expression and/or suppressed activation of patched homologue 1 (PTCH1), a tumour suppressor gene that forms part of the hedgehog signaling network, has been reported to be fundamental to the development of BCC." (PMID 17173689, 2006). "Ptch1 and Ptch2, both crucial in suppressing tumor growth in basal cell carcinoma (BCC) cells." (PMID 39900571, 2025). "Furthermore, Ptch1 influences the intracellular positioning of cyclin B1, linking its tumor-suppressive function to the regulation of cell division." (PMID 39900571, 2025). "PTCH1 alone does not result in a morphoeic phenotype being common to both mBCC and nodBCC; however, loss-of-function (as a potential tumour-suppressor gene) drivers FLNB and HECTD4 were identified as being morphoeic-specific." (PMID 41373535, 2025). "In summary, Ptch1 and Ptch2 may play an important role in tumor inhibition, and their functions overlap but are unique." (PMID 39900571, 2025). "In cancers with PTCH1::GLI1 fusions, the normal tumor-suppressive function of PTCH1 is disrupted." (PMID 39851545, 2025). "The PTCH1 mRNA levels were lower in patients with BCC compared to the control group, but an underexpression of its protein was found in the tumor tissue, which may be related to a Hedgehog deficient signaling that promotes cell growth and proliferation." (PMID 38287479, 2024).
tumor (continued). "Analyzing larger sample sizes and conducting comparisons between tumor tissue and healthy skin, as well as engaging in functional studies, could contribute valuable insights to the study of the PTCH1 gene and its role in cSCC." (PMID 38534460, 2024). "Conversely, the increase in apoptotic rates in GCPsC57Bl-Ptch1+/− after irradiation may prevent the accumulation of radiogenic DNA damage and reduce oncogenic potential, despite a higher spontaneous tumor incidence (40%)." (PMID 39594660, 2024). "This spontaneous apoptosis may clear potentially tumor-prone GCPs with Ptch1 LOH derived from replicative stress, contributing to the lower spontaneous tumor incidence (7.7%) in CD1Ptch1+/− mice." (PMID 39594660, 2024). "Interestingly, in the salivary tumors, the expression pattern of PTCH1 differs from the other analyzed tumor types: Healthy epithelium shows PTCH1 positivity, whereas none of the other tissues showed this pattern." (PMID 38731849, 2024). "In contrast to the liver BCC metastasis, the cutaneous in situ BCC had a lower tumor mutational burden, lacked PD-L1/2 amplification, and had a distinct PTCH1 mutation." (PMID 39429413, 2024). "PTCH1 pattern of staining shows an interesting pattern, where healthy samples are mostly positive in the stromal compartment, while the signal shifts to the tumor compartment in tumors." (PMID 38731849, 2024). "In addition to the CNV analysis, we also utilized high PTCH1 and PTCH2 expression (PTCH1/2 high) in comparison to the healthy skin cluster hKC to pinpoint BCC tumor cells." (PMID 39516494, 2024). "Ptch1+/− mice, irradiated at post-natal day 2 with a single dose of 3 Gy of X-rays, develop full-blown MBs starting from 10 weeks post-irradiation with maximum tumor incidence (60%) reached by 20 weeks." (PMID 37240259, 2023). "In addition to the overexpression of Hh ligands, most of these tumours are characterized by presenting an ectopic expression of PTCH1 and GLI." (PMID 36765685, 2023). "In a recent work from the Children’s Oncology Group (COG) in highly-differentiated fusion negative tumours, four out of 22 patients harboured mutations in the Hh pathway (three in PTCH1, one in SUFU)." (PMID 36765685, 2023). "While our observations do not prove that the CTD of PTCH1 encodes a tumour suppressor function, as we did not demonstrate sufficiency to cause transformation, they indicate an important regulatory role of key cancer cell properties." (PMID 36672319, 2023). "The Hedgehog receptor, Patched1 (PTCH1), is a well-known tumour suppressor." (PMID 36672319, 2023). "The Hh family receptor PTCH1 is a well-characterised tumour suppressor." (PMID 36672319, 2023). "Ptch1 in Type I can regulate apoptosis by recruiting proapoptotic elements such as caspase-9, dependence-associated receptor transmembrane (DRAL) and tumor-upregulated CARD (caspase-associated recruitment domain)-containing antagonist of caspase nine (TUCAN) to the C-terminal domain." (PMID 36517618, 2022). "Recently, tumor‐associated astrocyte secretion of Shh was shown to be required for Shh MB tumorigenesis, despite the absence of the Shh receptor Ptch1, indicating that a novel Ptch1‐independent Shh pathway is involved in MB progression." (PMID 34482626, 2022). "However, a novel PTCH1::GLI2 gene fusion was found in the tumor cells, instead of the previous reported characteristic MALAT1-GLI1 gene fusion or recent described EWSR1-CTBP1 fusion in gastroblastomas." (PMID 36147912, 2022).
tumor (continued). "In addition, multiple tumor types, including sarcomas and Wilms tumors, have been described in patients with GS due to 9q22.3 microdeletion encompassing the PTCH1 locus." (PMID 33860896, 2021). "Interestingly, MEN1611 increases apoptosis in Ptch1+/−/Tis21KO nodules, not only in the whole population of tumor cells, but also in the tumor stem cell CD15+ population, with consequent decrease of stem cell number." (PMID 34395258, 2021). "We identified nonsynonymous SNVs in tumor tissues, such as SMARCA4 (in 192D0360T and 192D0641T), BCOR and LRP1B in 192D0641T, as well as frameshift mutations of KMT2D in 192D0695T and truncating mutations of PTCH1 in 192D0583T." (PMID 33707557, 2021). "Additionally, loss-of-function mutations in the PTCH1 gene in the context of NBCCS, an autosomal dominant disorder predisposing to multiple BCCs, determine tumour permissive phenotypes in dermal fibroblasts." (PMID 34831015, 2021). "Hh signaling molecules, such as ligands (SHh), receptors (PTCH1) or transcription factors (GLI1/2) in the tumor tissue or body fluid, may reflect tumor progression, metastasis, drug sensitivity or treatment response." (PMID 33440657, 2021). "Specifically, these mutations are located on five tumor suppressors (SDHA, RB1CC1, PTCH1, DMBT1, BCR) and eight proto-oncogenes (MERTK, CSF1R, MYB, ROS1, PCM1, FGFR2, MYH11, BRCC3) and have an allele frequency lower than 0.01 in the Genome Aggregation Database (GnomAD)." (PMID 33466296, 2021). "It has been reported that multiple HFSC populations readily develop BCC-like tumours in Ptch1-deleted mice, and targeting Shh signalling pathway components, such as using smoothened inhibitors (e.g., vismodegib (Erivedge®) and sonidegib (Odomzo®), can treat BCC." (PMID 34380571, 2021). "Thus, in this study, we tested if the loss of the Btg1-dependent control of GCP proliferation is able to increase the spontaneous tumor incidence in an Shh-MB model, crossing Btg1 knockout mice to Patched1 heterozygous (Ptch1+/−) mice." (PMID 32231994, 2020). "Rescuing primary cilia may also have therapeutic benefit to patients with established disease by enabling tumour epithelial cells to regulate ectopic Hh activation through expression of negative regulators such as Ptch1." (PMID 32571902, 2020). "PTCH1 is typically described as a tumor suppressor by virtue of its inhibitory action toward SMO." (PMID 32957513, 2020). "No increase of proliferation is observed also in Ptch1+/−/Btg1KO vs. Ptch1+/−/Btg1WT tumor cells." (PMID 32231994, 2020). "Also in MB lesions and in tumor cells, i.e., in Ptch1+/− background, the deletion of Btg1 highly increases apoptosis." (PMID 32231994, 2020). "Moreover, the tumor suppressor role of PTCH1 has been demonstrated in PTCH1+/− mice that develop tumors and several features observed in patients with BCNS." (PMID 33113965, 2020). "In addition, alterations in the methylation status of PTCH1 gene were reported in different types of cancer, suggesting the epigenetic role of PTCH1 in tumor development." (PMID 33396427, 2020). "In a potential paracrine activation, Shh expression in the tumor cells can be associated with the increased interpretation of Ptch1 and Gli1 in the adjacent stromal cells, which was not evident in this series of experiments." (PMID 30769952, 2019). "Interestingly, such a mutation correlated with the splicing-dependent inactivation of the PTCH1 tumor-suppressor gene and activation of the GLI2 and CCND2 oncogenes in SHH-MB, supporting the biological relevance of U1 snRNA mutation in this tumor." (PMID 31861467, 2019).
tumor (continued). "It suggested that L-4 inhibited MB tumor growth by inhibiting Hh pathway and Gli1 and Ptch1 might be important pharmacodynamic markers." (PMID 30846937, 2019). "The occurrence of PTCH1 mutations that result in developmental anomalies concomitant with BCC expression serve as poignant reminder of the role of PTCH in normal tissue development and as a tumor suppressor gene (TSG), a basic tenet in cancer biology, including all TSGs identified to date." (PMID 30858923, 2019). "One tumor (patient #7) was found to have a disease associated variant HRAS c.182A > G p.(Q61R) as well as variants of uncertain significance in KIT c.287C > T p.(T96 M) and PTCH1 c.3617G > A p.(R1206H)." (PMID 31046843, 2019). "PTCH1 and GLI3 overexpression could be caused by a self-inhibiting mechanism of the pathway, since they are a tumor suppressor and a repressor effector, respectively." (PMID 30754660, 2019). "We advocate, therefore, that these patients should be followed up more frequently than patients whose tumours do not show PTCH1 under-expression or do not have underlying LS." (PMID 30379908, 2018). "In addition, while loss of PTEN in Ptch1+/− mice results in MB that respond to SMO inhibitors by stopping growth, the treated tumours fail to regress." (PMID 30068568, 2018). "Given these considerations, Ptch1 is considered a bona fide tumor suppressor." (PMID 29869097, 2018). "We identified few discordant mutations potentially impacting treatment outcome, (for example, EGFR, PTCH1), suggesting that heterogeneous parts of the tumours could respond differently to targeted drugs." (PMID 28186126, 2017). "Currently, chemotherapeutic adjuncts are seldom used in sporadic cases; although they may be helpful in cases with decreased PTCH1 expression in limiting tumor size, surgical margins and recurrence." (PMID 27066764, 2016). "EGFR23 and Ptch1/Shh24 pathways were activated and involved in tumor cell repopulation." (PMID 26961247, 2016). "Compared with the big deletions we found in the Ptch1 locus of CRISPR-PTCH1 tumours, the small insertions identified in the induced GBMs hint towards a very variable repair of CRISPR-induced double-strand breaks in vivo, potentially specific for the respective cell type or genomic locus." (PMID 26067104, 2015). "Next we attempted to characterize the tumor microenvironment in the skin and BCCs of Ptch1+/−/SKH-1 mice by profiling baseline and UVB-induced expression of cytokines, chemokines; inflammatory cell infiltration; pro-inflammatory signaling; and responses to non-steroidal anti-inflammatory agents." (PMID 26413810, 2015). "Of further interest in the process of reviewing skin biopsies obtained to assess tumor development in the Ptch1+/−/SKH-1 mice we found histologic evidence for a substantially increased pro-inflammatory response, a recognized contributor to the pathogenesis of cutaneous cancers." (PMID 26413810, 2015). "Tumors typically showed whole chr.9 loss, likely targeting multiple tumor suppressors (i.e. INK4A, PTCH1, and TSC1) whereas the cell lines had a high frequency of both gains and losses of chromosome 9, often in association with UPD affecting either the whole chromosome or its q-arm." (PMID 25997541, 2015). "Although mutations in PTCH1 in humans and Ptc heterozygous mice (ptc+/−) known to develop increased spontaneous medulloblastoma; however, the mechanisms that lead to tumor development were not known." (PMID 26633513, 2015).